HCG14 (HLA complex group 14)
Synonyms: dJ111M5.4
Gene: Long non-coding RNA gene on chromosome 6 (28,896,428 to 28,897,322, forward strand). Ensembl gene ENSG00000224157.
Diseases named in the same sentence as HCG14 in open-access papers:
HCG14 is named in the same sentence as 2 diseases in open-access papers, as found by Europe PMC text mining. Sharing a sentence is not in itself a finding about the gene and the disease. The quoted sentences say what the papers report.
Infertility (1 paper, 2020). "The variables included in the final predicting model were (hCG21, ratio of hCG21/hCG14, and main cause of infertility)." (PMID 32297865, 2020). "Here, through the multivariate multinomial logistic regression method, we have established a mathematical model to predict the probability of having an IUP, EP, or BCP in pregnant women subjected to ART using predictors of hCG21, ratio of hCG21/hCG14, and main cause of infertility." (PMID 32297865, 2020).
HCG14 also shares sentences with these, for which no sentence is quoted: Autoimmunity (1 paper).